RBM3 (RNA binding motif protein 3)
Diseases named in the same sentence as RBM3 in open-access papers (continued):
Sharing a sentence is not in itself a finding about the gene and the disease.
bladder cancer (6 papers, 2013 to 2025). "In particular, mechanistic studies on how RBM3 limits the development and progression of bladder cancer are limited." (PMID 36831493, 2023). "The aim of this study was to examine the prognostic impact of RBM3 expression in urinary bladder cancer." (PMID 23565664, 2013). "A clinical retrospective study including 259 bladder cancer patients showed that the low expression of RBM3 was an independent factor for poor prognosis of bladder cancer; this finding is closely related to the progression of bladder cancer and decreased overall survival of patients." (PMID 36831493, 2023). "In bladder cancer, the role of RBM3 is similar to that in other tumors." (PMID 36831493, 2023). "Moreover, IHC allows for biomarker analysis in a subcellular context, which is particularly relevant as it appears to be mainly the nuclear expression of RBM3 that carries prognostic significance in bladder cancer." (PMID 35109796, 2022). "While the findings in the present study are based on analyses of transitional cell carcinoma, it would also be of interest to examine RBM3 expression and its possible prognostic implications in other histological subtypes of bladder cancer, e.g. squamous cell carcinoma or adenocarcinoma." (PMID 23565664, 2013). "Along this line, it would also be of interest to investigate the impact of RBM3 as a predictor of response to platinum-based chemotherapy, both in the neoadjuvant, adjuvant and palliative setting, cisplatin being one of the cornerstones in the medical treatment of bladder cancer." (PMID 23565664, 2013). "The effect of siRNA-mediated silencing of RBM3 on chemosensitivity was examined in RT4 and T24 human bladder carcinoma cells in vitro." (PMID 35109796, 2022). "Of note, the only two studies on bladder carcinoma including the current one did not use methods other than IHC to evaluate RBM3 expression." (PMID 26577765, 2015).
colon cancer (6 papers, 2018 to 2023). "By contrast, the down-regulation of RBM3 in HCT116 colon-cancer cells using specific siRNAs decreases cell growth in culture; this decrease is partially overcome by treatment with prostaglandin E2, a product of cyclooxygenase-2 enzyme activity." (PMID 35328637, 2022). "RBM3 is a cold-shock protein that is involved in translation, and has been published as a potential biomarker for breast and colon cancer because of this role." (PMID 33310754, 2021). "Hypoxic and other adverse conditions that are detrimental to cell growth, RBM3 participates in the survival of colon cancer cells mainly through a COX-2 signal transduction mechanism." (PMID 34804951, 2021).
urothelial bladder cancer (6 papers, 2013 to 2022). "Reduced RBM3 levels in urothelial bladder cancer are associated with tumor progression and poor prognosis, while high RBM3 expression correlates with lower stage tumors and decreased risk of lymphovascular invasion." (PMID 27147467, 2016). "Specifically concerning urothelial bladder cancer, the only study currently published on this topic reported loss of RBM3 expression to be associated with clinically more aggressive tumors and to be an independent factor of poor prognosis." (PMID 26577765, 2015). "The results from this study show that reduced RBM3 expression is significantly associated with more aggressive tumours and an independent predictor of reduced survival in patients with urothelial bladder cancer." (PMID 23565664, 2013). "Loss of RBM3 expression is associated with clinically more aggressive tumours and an independent factor of poor prognosis in patients with urothelial bladder cancer and a potentially useful biomarker for treatment stratification and surveillance of disease progression." (PMID 23565664, 2013). "The association between RBM3 expression and a favorable clinical outcome has been demonstrated in several other cancer forms but this is, to our knowledge, the first report of the prognostic impact of RBM3 expression in urothelial bladder cancer." (PMID 23565664, 2013). "The results from this study suggest that immunohistochemical evaluation of RBM3 expression in urothelial bladder cancer specimens may be a valuable diagnostic and prognostic biomarker, and a useful tool for improved treatment stratification of patients suffering from the disease." (PMID 23565664, 2013). "In the present study, we examined the prognostic significance of RBM3 expression in tumours from a large prospective cohort of patients with urothelial bladder cancer." (PMID 23565664, 2013). "Immunohistochemical RBM3 expression was examined in tumours from 343 patients with urothelial bladder cancer." (PMID 23565664, 2013). "While upregulation of RBM3 expression in urothelial bladder cancer has been identified as an independent factor of a favourable outcome in studies encompassing tumours of all clinical stages, its prognostic and in particular predictive value in muscle-invasive bladder cancer (MIBC) remains unclear." (PMID 35109796, 2022). "Finally, decreased expression of RBM3 was associated with clinically more aggressive urothelial bladder cancers and treatment failure in metastatic testicular non-seminomatous germ cell tumors." (PMID 26577765, 2015). "The prognostic implications of RBM3 in urothelial bladder cancer have been evaluated in a few earlier studies of mixed non-muscle-invasive and muscle-invasive tumours." (PMID 35109796, 2022).
gastric adenocarcinoma (5 papers, 2014 to 2024). "In support of this finding, RBM3 has been previously implicated in cancer and reported to be overexpressed in esophageal and gastric adenocarcinoma with particularly high expression in those cancers with a background of intestinal metaplasia." (PMID 38604503, 2024). "In the upper digestive system, RBM3 is highly expressed in esophageal and gastric adenocarcinoma, and reduced RBM3 expression is an independent factor of reduced overall and recurrence-free survival in these patients." (PMID 28118608, 2017). "In contrast, in oesophageal and gastric adenocarcinoma, RBM3 expression was similar in primary tumours and lymph node metastases." (PMID 28800641, 2017).
pancreatic cancer (5 papers, 2018 to 2023). "The mechanistic basis for the association between RBM3 expression and a more aggressive phenotype of pancreatic cancer needs to be further elucidated." (PMID 29464064, 2018). "In addition, high RBM3 levels were significantly associated with reduced overall survival in pancreatic cancer." (PMID 31546614, 2019). "The influence of RBM3 expression on pancreatic cancer cell migration and invasion was then investigated." (PMID 29464064, 2018). "In summary, in line with the clinical data, RBM3 expression is demonstrated to confer a more aggressive behavior by enhanced migration and invasion of pancreatic cancer cells, but also an increased sensitivity to chemotherapy in vitro." (PMID 29464064, 2018). "In summary, this study provides a first description of the expression and prognostic significance of RBM3 in periampullary adenocarcinoma, including pancreatic cancer." (PMID 29464064, 2018). "After siRNA suppression of RBM3 in vitro, pancreatic cancer cells displayed reduced migration and invasion compared to control, as well as a significantly increased resistance to chemotherapy." (PMID 29464064, 2018). "Pancreatic cancer cells were transfected with anti-RBM3 siRNA in vitro and the influence on cell viability following chemotherapy, transwell migration and invasion was assessed." (PMID 29464064, 2018). "Suppression of RBM3 led to reduced sensitivity of MIAPaCa-2 pancreatic cancer cells to chemotherapeutic drugs." (PMID 29464064, 2018). "Herein, we examined the prognostic value of RBM3 in periampullary adenocarcinoma, as well as the effects following RBM3 suppression in pancreatic cancer cells in vitro." (PMID 29464064, 2018). "Contrastingly, in pancreatic cancer, high RBM3 levels correlated to reduced survival." (PMID 35109796, 2022). "Moreover, in vitro studies have reported decreased sensitivity to chemotherapy after RBM3 suppression in epithelial ovarian and pancreatic cancer cells." (PMID 35109796, 2022). "RBM3 enhanced cell migration and invasion of pancreatic cancer." (PMID 34804951, 2021). "In conclusion, the strong indication of a positive response predictive effect of RBM3 expression in pancreatic cancer may be highly relevant in the clinical setting and merits further validation." (PMID 29464064, 2018). "Thus, RBM3 is a promising biomarker candidate for improved treatment stratification of patients with periampullary and pancreatic cancer, and merits further study, in the clinical setting as well as in a functional context." (PMID 29464064, 2018). "RBM3 mRNA levels were examined in 176 pancreatic cancer patients from The Cancer Genome Atlas." (PMID 29464064, 2018). "Several downstream proteins have been discussed to be tumor regulator in pancreatic cancer, such as FBXO11, IL-6 and RBM3 except SLC38A2." (PMID 37005877, 2023). "The pancreatic cancer cells investigated display different levels of RBM3, where PANC-1 cells have high RBM3 expression, MIAPaCa-2 cells display moderate levels and BxPC-3 cells display low RBM3 expression." (PMID 29464064, 2018). "This implicates the existence of other, RBM3-independent, mechanisms involved in sensitivity or resistance to chemotherapy in pancreatic cancer, that may become of importance in some tumors with high RBM3 expression that do not respond to chemotherapy." (PMID 29464064, 2018).
brain injury (4 papers, 2020 to 2022). Acute and chronic (see also brain INJURIES, CHRONIC) injuries to the brain, including the cerebral hemispheres, CEREBELLUM, and brain STEM. "Another recent study investigating RBM3 knockout in mice after ischemic brain injury focusing on neural stem/progenitor cells (NSPC) shows that RBM3 plays an important role in neuronal regeneration after ischemic brain injury." (PMID 34776788, 2021). "In the subgranular zone of the adult rodent dentate gyrus, the small protein RNA-binding motif protein 3 (RBM3) promoted IGF-II expression and secretion by interacting with IMP2, thereby providing neuroprotection and neurogenesis after hypoxic–ischemic brain injury." (PMID 34072372, 2021).
Fever (4 papers, 2017 to 2024). Body temperature elevated above the normal range. "The previous study indicated that Rbm3 expression was reduced during fever/pyrexia, and reduced Rbm3 expression in turn led to elevated expression of Rbm3-targeted temperature-sensitive miRNAs (termed thermomiRs), such as miR-142-5p and miR-143." (PMID 38419081, 2024). "Induced RBM3 expression was observable up to 14 hours after rewarming to normothermia (37°C at 29, 31, and 41 h), 2 hours after further warming to pyrexia (31 h), and gradually returned to baseline levels after 24 hours." (PMID 31871429, 2019). "Moreover, cytoprotective Rbm3 expression was induced by cooling but suppressed by pyrexia in cardiomyocytes." (PMID 38419081, 2024). "However, prolonged exposure to pyrexia for 24 hours resulted in a significant suppression of RBM3 expression in all groups at the mRNA and protein levels (53 h)." (PMID 31871429, 2019). "Moreover, cytoprotective RBM3 expression was induced by cooling but suppressed by pyrexia, correlating with apoptotic caspase-3 activation." (PMID 31871429, 2019). "Additionally, we also investigated the effect of rebound pyrexia on RBM3 expression and further myocardial cell death after an acute ischemia-reperfusion injury." (PMID 31871429, 2019). "Moreover, our observation of suppressed RBM3 expression by pyrexia in the HL-1 cardiomyocytes corresponds with previous findings that showed that blood RBM3 mRNA levels were also decreased in febrile children." (PMID 31871429, 2019).
gastric cancer (4 papers, 2012 to 2026). A primary or metastatic malignant neoplasm involving the stomach. "RBM3 therefore represents a promising biomarker and potential therapeutic target in gastric cancer." (PMID 41994650, 2026).
Hypothermia (4 papers, 2019 to 2023). Reduced body temperature due to failed thermoregulation. "Hypothermia induces RBM3 protein expression in association with TrkB activation in vivo, but the exact molecular mechanism controlling RBM3 expression downstream of these signalling cascades and other modulators remains unclear." (PMID 37248947, 2023). "Hypothermia up‐regulates RNA‐binding motif protein 3 (RBM3), which is verified to protect synaptic plasticity." (PMID 32648620, 2020). "Hypothermia up-regulates a small protein subset that includes RNA-binding motif protein 3 (RBM3), which is neuroprotective under stressful conditions." (PMID 31484925, 2019).
prion disease (4 papers, 2020 to 2025). A transmissible disease that is caused by a protein that is able to induce abnormal folding of normal cellular proteins, leading to characteristic spongiform brain changes, which are associated with neuronal loss without an inflammatory response. "Evidence has demonstrated that RBM3 plays an important neuroprotective role of hypothermia through preventing neuronal loss and restoring synapse reassembly in Alzheimer's and prion disease models." (PMID 32648620, 2020). "We also identified Rbm3, a cold-shock protein that protects against prion disease, as highly expressed by prion-resistant hippocampal neurons and upregulated in prion disease." (PMID 39580485, 2024). "Rbm3 upregulation combined with decreased Egr1 and Rab6b was readily detected at the clinical endpoint of prion disease, but not at earlier timepoints." (PMID 39580485, 2024).
astrocytomas (3 papers, 2015 to 2024). "Furthermore, RBM3 was reported to be associated with tumors’ grades as poorly differentiated prostate tumors and high-grade astrocytomas showed higher mRNA and immunoexpression of RBM3 when compared to well-differentiated and low-grade tumors." (PMID 26577765, 2015). "RBM3 was able to perfectly discriminate human high-grade astrocytomas/glioblastomas and control tissues." (PMID 39507532, 2024). "At the same time, RBM3 high expression has been shown to be correlated with high grade astrocytoma compared with low grade or normal tissue." (PMID 28118608, 2017). "The mRNA expression level assessment, western blotting and immunohistochemical staining results have demonstrated that RBM3 was up-regulated in human astrocytomas compared with normal brain tissues." (PMID 28118608, 2017). "RBM3 also exhibits neuroprotection functions in nerve cells, so the associated protein activation in astrocytoma may be not essential in non-neuronal cell." (PMID 28118608, 2017). "Additionally, a higher astrocytoma grade suggested stronger RBM3 expression, indicating that RBM3 overexpression might have proliferative and/or proto-oncogenic functions in humans." (PMID 28118608, 2017).
glioblastoma (3 papers, 2022 to 2025). The most malignant astrocytic tumor (WHO grade IV). "Snrpb is associated with glioblastoma, and Rbm3 is involved in neuronal activity, neurogenesis, and synaptic vesicle dynamics in damaged brains." (PMID 36614117, 2022).
ischemic stroke (3 papers, 2022 to 2025). A stroke disorder caused by obstruction of blood flow to the brain, due to thrombotic (local blood clot formation) or embolic (due to a blood clot or other material traveling from another site) event. "Our study found that RBM3 was elevated in the test group and was associated with a good prognosis, which provided convincing evidence for RBM3 as a novel therapeutic target in ischaemic stroke." (PMID 36873429, 2023). "At the same time, although therapeutic hypothermia is considered to have considerable potential in the treatment of ischaemic stroke, the specific role of RBM3 in treatment is still unclear." (PMID 36873429, 2023). "Meanwhile, RBM3 has been widely studied and, as discussed in this mini-review, may play a beneficial role in ischemic stroke." (PMID 40124786, 2025). "Our study shows the association of FGF21 and RBM3 on the prognosis of ischemic stroke patients, and supports the development of new pharmacological tools for RBM3-mediated neuroprotection in the absence of hypothermia." (PMID 35207221, 2022). "In line with previous in vivo experimental studies, we have recently reported that the RNA-binding motif protein 3 (RBM3), a member of CSPs, mediates the good prognosis of ischemic stroke patients with mild body temperatures." (PMID 35207221, 2022).
lung carcinoma (3 papers, 2019 to 2023). "The aim of the present study was to examine the prognostic value of RBM3 protein and mRNA expression in non‐small cell lung cancer (NSCLC)." (PMID 32491279, 2020).
metastatic melanoma (3 papers, 2011 to 2018). A melanoma that has spread from its primary site to another anatomic site. "However, studies in metastatic melanoma and other cancers find that high RBM3 expression is associated with reduced invasiveness." (PMID 29743635, 2018). "In line with previous in vitro data, we here show that RBM3 is down-regulated in metastatic melanoma and high nuclear RBM3 expression in the primary tumour is an independent marker of a prolonged OS." (PMID 21777469, 2011).
squamous cell carcinoma (3 papers, 2013 to 2020). A carcinoma arising from squamous epithelial cells. "Also, the expression levels of RBM3 mRNA were investigated in 2087 lung adenocarcinomas and 899 squamous cell carcinomas assembled from 13 and 8 public gene expression microarray datasets, respectively." (PMID 32491279, 2020). "The RBM3 mRNA levels were not clearly associated with patient outcome in either adenocarcinomas or squamous cell carcinomas." (PMID 32491279, 2020). "Our data further suggest, that RBM3 might play a comparable role in squamous cell carcinomas." (PMID 30419865, 2018).
Stroke (3 papers, 2022 to 2025). Sudden impairment of blood flow to a part of the brain due to occlusion or rupture of an artery to the brain. "To understand the relationship between FGF21 and RBM3 in a clinical scenario such as stroke, we evaluated the associations between the circulating concentrations of both proteins and the outcome of stroke patients, and how body weight and temperature influence this response." (PMID 35207221, 2022). "In line with this, an increase in Rbm3 levels following pharmacological hypothermia was related with better outcomes in stroke mice." (PMID 40124786, 2025). "Higher concentrations of FGF21 were found on admission, while the peak for RBM3 expression was observed 72 h after stroke onset." (PMID 35207221, 2022). "The RNA-binding protein motif 3 (RBM3) is a well-known cold shock protein with beneficial roles following a stroke in both animal models and humans." (PMID 35409112, 2022). "In our previous analysis and this new study, RBM3 was detected in blood using a commercial ELISA kit, and the mean age of the stroke patients included was >50 years." (PMID 35207221, 2022). "In addition, pharmacological hypothermia using phenothiazine drugs (chlorpromazine and promethazine, an antipsychotic and a first-generation antihistamine, respectively) also resulted in increased RBM3 expression up to 24 h in a stroke mouse model." (PMID 40124786, 2025). "Fibroblast growth factor 21 (FGF21) is an obesity- and temperature-related hormone that upregulates the expression of RBM3, which is beneficial as a recombinant treatment and has been tested under different experimental pathological conditions, including stroke." (PMID 35207221, 2022). "Targeting the RBM3 pathway is a promising strategy to benefit from cooling as treatment for stroke without its negative side effects." (PMID 40124786, 2025). "Pharmacological induction of RBM3 represents a potential means of neuroprotection for stroke in the absence of hypothermia; however, a drug or agonist that directly targets RBM3 expression or activity has not been developed." (PMID 35207221, 2022). "However, the interaction between RBM3 and FGF21 has not yet been tested for clinical stroke conditions." (PMID 35207221, 2022).